MYOD1 (myogenic differentiation 1)
Diseases named in the same sentence as MYOD1 in open-access papers (continued):
Sharing a sentence is not in itself a finding about the gene and the disease.
kidney stones (1 paper, 2024). "This study aims to uncover the molecular mechanisms underlying pediatric kidney stone formation induced by renal calcium deposition by utilizing high-throughput sequencing data to reveal the regulation of PINK1 by MyoD1." (PMID 39242558, 2024). "The results indicate that overexpression of PINK1 can reverse the downregulation of PINK1 and the kidney stone-related protein OPN caused by knockdown of MyoD1." (PMID 39242558, 2024). "The results demonstrate that under the successful establishment of the kidney stone model, sh-MyoD1 and Ad-PINK1 exhibit highly desirable knockdown and overexpression efficiencies." (PMID 39242558, 2024). "We identified MyoD1 as an upstream transcription factor of PINK1 that contributes to the occurrence of pediatric kidney stones through the activation of PINK1." (PMID 39242558, 2024). "This study explores the molecular mechanism of MyoD1-mediated mitochondrial homeostasis regulation in the induction of pediatric kidney stone formation through the transcriptional activation of PINK1 expression." (PMID 39242558, 2024). "In this study, we discovered that MyoD1 may promote kidney stone formation and development in pediatric patients by transcriptionally activating PINK1 to induce mitochondrial oxidative stress." (PMID 39242558, 2024). "In summary, this study preliminarily concludes the following: MyoD1 may promote the occurrence and development of kidney stones through transcriptional activation of PINK1 expression, which in turn promotes mitochondrial oxidative stress." (PMID 39242558, 2024). "Our in vivo and in vitro experiments confirm that silencing MyoD1 could inhibit mitochondrial oxidative stress and kidney stone formation in rats by downregulating the expression of PINK1." (PMID 39242558, 2024). "This study reveals for the first time that MyoD1 may regulate mitochondrial homeostasis and induce pediatric kidney stone formation by transcriptionally activating the expression of PINK1, shedding light on the possible mechanism behind it." (PMID 39242558, 2024). "This study utilized a rat model of kidney stones to confirm the inhibitory effect of silencing MyoD1 on PINK1 expression, which could regulate mitochondrial oxidative stress and impact kidney stone formation." (PMID 39242558, 2024). "It is hypothesized that MyoD1 could affect the occurrence of kidney stones by activating the transcription of PINK1." (PMID 39242558, 2024). "We found that silencing MyoD1 could inhibit the formation of kidney stones by downregulating PINK1 expression in both in vitro and in vivo kidney stone models, providing new insights into the pathogenesis of pediatric nephrolithiasis." (PMID 39242558, 2024). "In addition, our findings also provide potential targets for developing new strategies to treat pediatric kidney stones, such as developing drugs that could inhibit the expression of MyoD1 or PINK1." (PMID 39242558, 2024). "In the future, we will further investigate the dynamic expression and function of MyoD1 and PINK1 in pediatric nephrolithiasis, aiming to reveal their more detailed molecular mechanisms in the disease progression." (PMID 39242558, 2024). "Although the functions of MyoD1 and PINK1 have been extensively studied in other diseases, their roles in pediatric kidney stones still need to be clarified." (PMID 39242558, 2024). "By incorporating the studies of MyoD1 and PINK1 into the field of kidney stones, this research provides a new perspective for understanding the pathogenesis of kidney stones." (PMID 39242558, 2024). "The results indicate that during the process of kidney stone formation, PINK1, as a downstream molecule of MyoD1, can enhance mitochondrial autophagy, thereby promoting cell apoptosis and accelerating the progression of kidney stones." (PMID 39242558, 2024).
kidney stones (continued). "This study provides insights into the potential roles of MyoD1 and PINK1 in pediatric nephrolithiasis, offering a novel perspective for understanding the pathogenesis of this disease." (PMID 39242558, 2024). "By analyzing the differential expression in pediatric renal calculi, we identified four differentially expressed genes: CTCFL, MYH11, MyoD1, and PAX5." (PMID 39242558, 2024). "Through experimental verification, we will reveal how MyoD1 activates the transcription of PINK1, thereby impacting mitochondrial oxidative stress and promoting the occurrence of kidney stones." (PMID 39242558, 2024). "The correlation analysis results indicate a strong positive correlation between the expression of MyoD1 and PINK1, and they both show an upregulation trend in pediatric kidney stones." (PMID 39242558, 2024). "Another important finding of this study is that MyoD1 is an upstream transcription factor of PINK1, which could participate in developing pediatric kidney stones by activating PINK1." (PMID 39242558, 2024). "At the same time, we will validate our findings in a larger clinical sample to evaluate whether MyoD1 and PINK1 could serve as potential targets for treating pediatric kidney stones." (PMID 39242558, 2024). "Although MyoD1 has been shown to have the ability to influence mitochondrial function in other diseases, this ability has not been reported in the formation process of kidney stones." (PMID 39242558, 2024). "Although it is known that MyoD1 could regulate the expression of many genes, this is the first time that it has been found to activate the expression of PINK1 and affect the formation of pediatric kidney stones." (PMID 39242558, 2024). "Finally, we will also attempt to develop drugs that could suppress the expression of MyoD1 or PINK1, providing new strategies for treating pediatric kidney stones." (PMID 39242558, 2024). "Our in vivo and in vitro experiments collectively confirmed that silencing MyoD1 could inhibit mitochondrial oxidative stress, mitochondrial autophagy, and cellular apoptosis in a rat model of kidney stones by downregulating PINK1 expression, consequently suppressing the formation of kidney stones." (PMID 39242558, 2024). "The results indicate that the absence of MyoD1 and PINK1 is of significant importance for maintaining the integrity of mitochondrial membrane structure during the process of kidney stone formation." (PMID 39242558, 2024).
metastatic disease (1 paper, 2022). "Over the past decade, improvements in RMS survival rates of more than 70% for patients with localized disease were achieved but new treatment options are still required for patients with metastatic disease or aggressive molecular features such as somatic mutations in MYOD1." (PMID 36430468, 2022).
mucinous carcinomas (1 paper, 2018). "There are six genes (MAL, MYOD1, OSMR, SEPTIN9, SFRP1, and SFRP4) for which hypermethylation is observed almost exclusively or preferentially in mucinous carcinomas." (PMID 29882921, 2018).
myeloid malignancies (1 paper, 2009). "As well as genes predominantly methylated in certain HN subtypes, we also identified six genes, i.e. DBC1, DIO3, FZD9, HS3ST2, MOS and MYOD1, that were significantly hypermethylated in B-cell, T-cell and myeloid malignancies." (PMID 19750229, 2009). "As well as identifying genes showing aberrant DNA methylation in certain HN subtypes, we also detected six genes—DBC1, DIO3, FZD9, HS3ST2, MOS, and MYOD1—that were significantly hypermethylated in B-cell, T-cell, and myeloid malignancies." (PMID 19750229, 2009).
osteoarthritis (1 paper, 2014). A noninflammatory degenerative joint disease occurring chiefly in older persons, characterized by degeneration of the articular cartilage, hypertrophy of bone at the margins and changes in the synovial membrane. "These include genes associated with cartilage formation (SOX6), inflammation and osteoarthritis (SAA) and muscle cell differentiation and muscle regeneration (MYOD1, SERGEF)." (PMID 25270232, 2014).
paraganglioma (1 paper, 2024). A benign or malignant neoplasm arising from paraganglia located along the sympathetic or parasympathetic nerves. "Immunohistochemical findings for paragangliomas are as follows: S-100 positivity; positivity for neuroendocrine markers such as NSE, CgA and Syn but not MyoD1, Des or others; and PAS positivity without positive cytoplasmic particles." (PMID 38291475, 2024).
ptosis (1 paper, 2025). The drooping of the upper eyelid. "In contrast, Foxk2fl/fl; Myod1-Cre mice exhibited damaged mitochondria with indistinct cristae, similar to the mitochondrial morphology observed in the EM of individuals with congenital ptosis." (PMID 40410591, 2025).
sarcomatoid carcinoma (1 paper, 2024). A malignant epithelial neoplasm characterized by the presence of spindle cells and anaplastic morphologic features. "For example, in the case of sarcomatoid carcinomas, mesenchymal markers such as S100, myogenin, and MYOD1 are used for staining, which varies according to the specific subtype." (PMID 39001412, 2024).
Skeletal myopathy (1 paper, 2023). "Therefore, decreased MyoD1 in TAFAZZIN-deficient myoblasts may serve as the mechanism underlying the development of skeletal myopathy in BTHS patients." (PMID 36739949, 2023). "Our findings indicate a new regulatory role for CL in muscle development and potentially identify a new treatment strategy for BTHS skeletal myopathy based on MyoD1-targeted therapy." (PMID 36739949, 2023). "Our study suggests a new regulatory pathway that links CL with muscle development and thus identifies a potential new avenue for treating skeletal myopathy in BTHS patients by targeted elevation of MyoD1 expression." (PMID 36739949, 2023).
solitary fibrous tumor (1 paper, 2025). Solitary fibrous tumor (SFT) represents a diverse group of ubiquitous rare spindle cell neoplasms that may be benign or malignant and that most frequently arises from the pleura and peritoneum and rarely from other sites such as head and neck, liver and skeletal muscle. "Immunohistochemical analysis demonstrated positivity for CD34, STAT6, MyoD1, α-SMA, Bcl-2, and CD99, confirming the diagnosis of extrapleural dedifferentiated solitary fibrous tumor (DSFT)." (PMID 40728762, 2025).
Zinc deficiency (1 paper, 2025). A deficiency of the essential metal Zinc; an essential cofactor for many enzymes. "As in the early phase, Myod1 expression remained stable, while Myog was downregulated by zinc deficiency." (PMID 41347147, 2025).
tumor (156 papers, 1991 to 2026). "Literature reports indicate that the recurrence rate of cervical ERMS in adults can reach 20%–40%, potentially due to occult micrometastases or tumor biological characteristics (e.g., fusion gene negativity and MYOD1 mutations)." (PMID 40703554, 2025). "In 7/9 patients who had an event, the tumor was MYOD1 L122R mutated and in all the cases the event included a distant relapse." (PMID 36980529, 2023). "The first was derived from a 17-year-old female and the second from a 24-year-old female, both affected by SSRMS and with MyoD1 mutation, which is a hallmark of tumor aggressiveness." (PMID 34067464, 2021). "Among seven cases of sclerosing RMS displaying MYOD1 mutations, four cases also displayed focal areas of tumor with spindle-shaped tumor cells." (PMID 27562493, 2016). "Thus, in RMS, MYOD1 is prevented from binding E-boxes that enable differentiation, while maintained or redirected to stem and proliferation associated E-boxes to promote tumor survival and proliferation." (PMID 39902277, 2024). "Immunohistochemical staining revealed positive expression of Myogenin, MyoD1 and Desmin in the tumor cells." (PMID 40520793, 2025). "Our previous studies utilizing the NSG mouse tumor model demonstrated a significant increase in Pax7 expression and a notable decrease in Myod1 in the GA muscles of tumor-bearing, vehicle-treated mice compared to tumor-free controls." (PMID 39996717, 2025). "Immunohistochemically, the tumor cells are positive for desmin and exhibit heterogeneous nuclear staining for myogenin and MYOD1." (PMID 40282503, 2025). "Immunohistochemistry: the tumor cells expressed Myogenin (11/13), Desmin (13/13), MyoD1 (12/13) and Myoglobin (5/9)." (PMID 40161378, 2025). "Immunophenotyping tests showed positivity of tumor cells for Desmin, Myogenin, MyoD1, Syna, CD56, and ALK." (PMID 38835374, 2024). "Immunohistochemistry showed positive staining for cell CyclinD1, CD10, Caldesmon, and Vimentin in the tumor cells, with some tumor cells also demonstrating positive labeling for MyoD1, CKpan, and Myogenin." (PMID 39009979, 2024). "In the tumor samples available for immunohistochemistry, heterogeneous desmin positivity (12/13), inconstant MYOD1 (12/13) and myogenin (9/13) expression, and at least partial ALK (9/13) positivity were observed." (PMID 38168093, 2024). "The tumor cells in this case diffusely expressed Desmin, Myogenin, and MyoD1, which can lead to the diagnosis of ARMS." (PMID 38835374, 2024). "Immunohistochemistry reveals tumor cells’ reactivity to vimentin, desmin, actin, myoglobin, MyoD1, and myogenin." (PMID 36777814, 2023). "The TF SIX1 maintains the cells in an undifferentiated state by reprogramming MYOD1 to occupy loci that drive tumor growth instead of muscle differentiation." (PMID 37345159, 2023). "Loss of SIX1 restores the MYOD1/MYF4 gene regulatory network, induces tumor cell differentiation, and inhibits in vivo tumor growth." (PMID 37345159, 2023). "Immunohistochemically, apart from desmin and focal SMA immunoreactivity, tumor cells also displayed multifocal myoD1 and focal myogenin positivity." (PMID 35642345, 2023). "One MCP tumor used for the analysis was distinct from the others and expressed lower levels of Myogenin and MyoD1, prompting us to investigate the heterogeneity present between MCP tumors." (PMID 37968277, 2023). "To gain insight into the mechanism of decrease in tumor size, we stained the tumor sections for Ki67 and myogenic markers (MYOD1 and MYOG1) as surrogates for proliferation and differentiation." (PMID 36037042, 2022). "MYOD1 has been reported to be expressed and to be functionally abnormal in a variety of tumor types." (PMID 36118887, 2022). "Microscopically, numerous histiocytes and foamy cells covered the actual tumor cells that were positive for desmin, MyoD1, and myogenin, suggesting striated skeletal muscle cell differentiation." (PMID 34128847, 2021).
tumor (continued). "The diagnosis of embryonal RMS was confirmed using myoD1 antibody which showed strong and diffuse intranuclear staining of the tumour cells." (PMID 33516251, 2021). "The tumor was composed of epithelioid and spindle areas with extensive necrosis, and immunohistochemistry showed positivity with pancytokeratin, Desmin and MyoD1, which were all noted in an external pathology report." (PMID 34514574, 2021). "Similar to the IHC data, the tumor-bearing vehicle-treated group displayed a significant increase in relative transcript levels of Pax7 and a significant decrease in Myod1 compared to the tumor-free vehicle-treated group." (PMID 33718372, 2021). "The characterization of this cell line has further contributed to define the characteristics of the rare group of SRF-NCOA2 neoplasms and their rhabdomyoblastic nature, clearly demonstrated by MYOD1 and myogenin expression by tumor cells." (PMID 34067464, 2021). "In agreement, loss of pro-differentiation factors or silencing/downregulation of tissue-specific genes is a common feature of tumorigenesis, and many tumor suppressors are pro-differentiation factors, including MYOD1." (PMID 33468253, 2021). "Immunohistochemically, the tumor cells exhibited a diffuse positive nuclear staining for MyoD-1, cytoplasmic staining for desmin, and smooth muscle actin (SMA)." (PMID 34067464, 2021). "The MYOD1 plays a crucial role in accelerating the transcription of p21 (a cyclin dependent kinase that acts as a tumor suppressor) and myogenin to remove the cells from cell cycle and terminate multiplication of differentiated myocytes." (PMID 34722422, 2021). "It is already known that decitabine demethylates tumor-suppressor genes such as p15INK4b, E-cadherin and MYOD1, making it efficacious in treating various malignancies in which these genes play a crucial role." (PMID 34358067, 2021). "Typical myogenic factors such as MyoD1 and myogenin are expressed by tumor cells and routinely used to define the diagnosis of RMS." (PMID 33362864, 2020). "Using hybrid-PCR, a cDNA library was first produced to screen the candidate host mRNA targets for miR-M2-5p and two host genes RBM24 and MYOD1, known for their important roles in tumor induction, were identified as its biological targets." (PMID 33224130, 2020). "Tumor cells were strongly positive for MyoD1, desmin, and myogenin, and weakly positive for actin, CD56, and PGP9.5." (PMID 31870387, 2019). "In contrast to Hes1, the transcription factor Myod1 identified a subset of tumor cells that remained proliferative after vismodegib treatment." (PMID 31863004, 2019). "On immunohistochemical analysis the tumor cells were strongly positive for MyoD1, myogenin, and the neuroendocrine cell marker PGP9.5, and weakly positive for desmin, actin, vimentin, CD56, and Syn." (PMID 31870387, 2019). "Analysis of vehicle-treated tumor sections demonstrated MYOD1-expressing cells throughout the tumors." (PMID 31863004, 2019). "In all cases, the tumor cells were positive for at least a single skeletal muscle-specific marker, namely MYOD1 and or myogenin." (PMID 27562493, 2016). "Alterations of methylation levels occurring in the promoter of the human MYOD1 gene have been reported in RMS tumours, with partially methylated MYOD1 up-stream regions present essentially in ERMS subtypes." (PMID 27764816, 2016). "In component B, the tumor cells were positive for desmin, MyoD1, myogenin, CD56, and CD10 and negative for the other antibodies." (PMID 23533892, 2013). "MYOD1 promoter methylation was detectable in tumor and normal colorectal samples, but was significantly higher in tumor than in normal mucosa." (PMID 22496748, 2012). "These distant masses appeared histologically consistent with the primary tumor and also displayed positive MyoD1 and myogenin immunoreactivity." (PMID 21559211, 2011). "Both the elbow emboli with the extratumoral foci of FRMS and the intratesticular tumor were positive for Myogenin, MyoD1, Vimentin and Desmin." (PMID 20701800, 2010).